IL2 (interleukin 2)
Diseases named in the same sentence as IL2 in open-access papers (continued):
Sharing a sentence is not in itself a finding about the gene and the disease.
alopecia areata (14 papers, 2015 to 2025). Loss of scalp and body hair involving microscopically inflammatory patchy areas. "To date, genome-wide association studies identified only a few susceptibility loci for alopecia areata associated with Th cytokines such as IL-2/IL-21 and IL-13." (PMID 34943905, 2021). "Previous studies have indicated that patients with alopecia areata exhibit increased IL-2 mRNA expression in the deep dermis surrounding hair follicles, with particularly high levels in active lesional areas." (PMID 40352276, 2025). "Studies have shown a positive relationship between alopecia areata severity and serum concentrations of several cytokines, including IL-2, TNF, IL-12, IL-17, and IL-17E." (PMID 41002719, 2025). "In the alopecia areata group, IL-2 levels averaged 0.365 ± 0.146 pg/mL, with a median of 0.315 pg/mL, closely resembling the control group, which exhibited an average of 0.367 ± 0.312 pg/mL and a median of 0.260 pg/mL." (PMID 40352276, 2025). "For example, IL-2 treatment to boost T-regs have shown promising results of hair regeneration in patients with alopecia areata." (PMID 36189219, 2022). "According to the literature, a positive correlation was reported between the severity of alopecia areata and the serum level of various cytokines including IL-2, TNF, IL-12, IL-17, and IL-17E." (PMID 34943905, 2021). "In a murine model of alopecia areata induced by scalp xenografts and inoculation of PBMCs stimulated in vitro with IL-2, an increase in the number of NKT1 cells was observed." (PMID 34594157, 2021). "Alopecia areata is characterized by systemic dysregulation of Th1 (IL-2, IFN-γ, TNF and IL-12), Th2 (IL-6), and Th17 (IL-17, IL-21) cytokines." (PMID 34943905, 2021). "As early as in 2014, an open-label pilot trial using low-dose IL-2 therapy in five patients with alopecia areata was published." (PMID 33868284, 2021). "Positive correlations between the severity of alopecia areata and an increased serum level of various cytokines including IL-2, TNF, IL-12, IL-17, and IL-17E were reported in the literature." (PMID 34943905, 2021). "Numerous studies described an increased serum level of IL-2 in patients with alopecia areata in comparison with healthy controls." (PMID 34943905, 2021). "Several susceptibility loci for alopecia areata were identified: CTLA-4, IL-2, IL-2RA, HLA, ULBP, and Eos." (PMID 29928283, 2018). "Given the promising data of LD IL-2 in patients with HCV, GVHD, and Alopecia areata, there is great interest in giving LD IL-2 to patients with T1D to specifically boost Treg numbers and activity." (PMID 26793191, 2015). "Moreover, higher levels of IL-2 mRNA were detected in peripheral blood mononuclear cells in patients with alopecia areata compared to control subjects." (PMID 34943905, 2021). "Similarly, in a murine model of alopecia areata, inoculation of IL-2-pulsed PBMCs previously exposed to NKT10 cells led to the inhibition of the generation of alopecic lesions, demonstrating the protective role of NKT10 cells in this disease." (PMID 34594157, 2021). "Based on our analysis, it may be suggested that alopecia areata is characterized by the dysregulation of systemic Th1 (IL-2, IFN-γ, TNF and IL-12), Th2 (IL-6), and Th17 (IL-17, IL-21) cytokines." (PMID 34943905, 2021). "Expanding on this, our study examined a broader range of cytokines, including IL-2, IL-4, IL-6, IL-10, IFN-γ, and TNF-α, to evaluate their potential correlation with the onset and progression of alopecia areata in blood assays." (PMID 40352276, 2025). "The dysregulation of the serum level of Th1, Th2 and Th17 cytokines including proinflammatory markers, such as IL-2 and TNF, indicates that alopecia areata is a systemic inflammatory disorder not limited to the hair follicles." (PMID 34943905, 2021).
alopecia areata (continued). "Although the variations in cytokines and vitamins such as IL-2, IL-4, IL-6, IL-10, TNF-α, and vitamins in the blood are insufficient to differentiate alopecia areata, we have observed a notable increase in IFN-γ and decrease in IgG4 levels among patients with this condition." (PMID 40352276, 2025). "Alopecia areata lesions also exhibit upregulated expression of genes, such as CCL19, IL-2, IL-15/IL-15RA, IL-2RA/IL-2RB, and Janus kinase 3 (JAK3) responsible for T cell migration and activation compared to regions with normal hair growth in alopecia areata patients." (PMID 29928283, 2018).
Cirrhosis (14 papers, 2013 to 2025). A chronic disorder of the liver in which liver tissue becomes scarred and is partially replaced by regenerative nodules and fibrotic tissue resulting in loss of liver function. "A recent study showed that in response to bacterial invasion, IL-2 pro-inflammatory cytokine secreted by immune cells affects T helper cells and decreases humoral immunity in advanced cirrhosis." (PMID 38473721, 2024). "In advanced cirrhosis, IL-2 pro-inflammatory cytokine is secreted by cells as a response to bacteria translocation." (PMID 38473721, 2024). "Insufficient attention has been paid to IL-2 and IL-10 in the field of cirrhosis, which indicate potential avenues for further research." (PMID 37872967, 2023). "GO:0045076 regulates the process of IL-2 in fibrosis, which has also been proven in patients with cirrhosis and ascitic fluid." (PMID 33519923, 2020). "Il2 signaling events mediated by PI3K, Mitotic metaphase/anaphase transition, and Prostanoid ligand receptors were also significantly associated with cirrhosis." (PMID 23894275, 2013). "Three pathways were observed to be associated with cirrhosis with a p(DS) value<0.001, FDR odds ratio adjusted p-value<0.01: “Il2 signaling events mediated by PI3K”, “Mitotic metaphase/anaphase transition”, and “Protanoid ligand receptors”." (PMID 23894275, 2013). "And this is consistent with previous reports that norfloxacin could enhance a regulatory T cell-mediated inflammatory control in cirrhosis by maintaining low IL-2 and IFN-γ levels and stimulating IL-10 production." (PMID 31428083, 2019). "Additionally, patients with cirrhosis who had LSM ≥25 kPa showed the lowest values of plasma cytokines [Th1 (IL-2 and TNF-α) and Th17 (IL-17A)]." (PMID 30400258, 2018). "Additionally, HIV/HCV-coinfected patients with advanced cirrhosis (LSM ≥25 kPa) had the lowest plasma values of cytokines related to Th1 (IL-2 and TNF-α) and Th17 (IL-17A) response." (PMID 30400258, 2018). "Indeed, studies have reported both an increase and a decrease in the frequency of circulating Tfh cells, the function of which could be hampered by elevation of IL-2 in advanced cirrhosis." (PMID 36505417, 2022). "The enhanced hepatic expression of IL‐2, IL‐5, IL‐13, or CXCL9 has been described in the context of schistosomiasis progression and generally in cirrhosis." (PMID 40751475, 2025). "Therefore, we explored the effect of the pro‐inflammatory properties of IL‐2‐330 (rs2069762), IL‐8 (rs2227306), TNF‐α−857 (rs1799724), and TNF‐α−1031 (rs1799964) versus the anti‐inflammatory properties of IL‐10‐1082 (rs1800896), IL‐10‐592 (rs1800872) on the risk of cirrhosis." (PMID 39315805, 2024). "Higher frequencies of M-MDSC in patients with cirrhosis correlated with reduced levels of S1-induced IFN-γ and IL-2." (PMID 37928515, 2023). "Increasing functions of IL-2 have proven to be resistant to microorganism infection and regulation of Tregs growth, survival and activity, which play a role in IBD, cirrhosis, and itchy psoriasis." (PMID 29492783, 2018). "A key finding was that the frequency of M-MDSC significantly correlated with S1-induced IFN-γ and IL-2 in cirrhotic patients, but not in healthy controls, which is in line with a more immunosuppressive MDSC phenotype in cirrhosis." (PMID 37928515, 2023).
edema (14 papers, 2013 to 2024). An abnormal accumulation of fluid beneath the skin, or in one or more cavities of the body. "In animal studies, it was discovered that IL-2 can cause pulmonary edema by increasing vascular permeability." (PMID 37761997, 2023). "Treatment with high doses (due to the very short half-life) of IL-2 causes vascular leak syndrome, pulmonary edema, hypotension and heart toxicities, as well as expansion of the immunosuppressive Tregs." (PMID 28915646, 2017). "However, a recent report by the group of Boyman has shown that vascular leak syndrome, which leads to severe pulmonary edema, is caused by the direct interaction of IL2 with its high affinity receptor expressed in lung epithelial cells." (PMID 24376444, 2013). "This chip mimicked the alveolar-capillary interface of a human lung, reproducing drug toxicity–induced pulmonary edema observed in human cancer patients treated with interleukin-2 (IL-2) at similar doses in the same time frame." (PMID 36014122, 2022). "This supports the conclusion that beyond the known ability of IL-2 to stimulate vascular leak and pulmonary edema, the lung environment is extremely sensitive to rapid IL-2-dependent induction of inflammatory cytokines and chemokines, even in the absence of infection." (PMID 31412088, 2019). "In contrast to unmodified IL-2, which can induce splenomegaly and pulmonary edema due to increased vascular permeability, CBD-IL-2 avoids these adverse effects." (PMID 39664443, 2024). "IL-2 signaling via low-affinity receptors present in the endothelium promotes vascular leak syndrome (VLS), leading to pulmonary edema, severe hypotension, and liver cell damage." (PMID 30379932, 2018). "It has previously been identified that IL-2 can induce pulmonary edema through IL2Rα on pulmonary non-immune cells in immune-depleted murine tumor models." (PMID 33986267, 2021).
bacteremia (13 papers, 2015 to 2025). "Peak serum levels of MIP-1a, MIP-β, G-CSF, VEGF, TNF, IL-2 and IL-12 (p40) were observed after the bacteremia was controlled for both groups." (PMID 35925895, 2022). "Compared to bacteremia patients, candidemia patients had only IL-2 cytokine in significantly elevated levels." (PMID 34684298, 2021). "A study carried out with monocytes from healthy donors which were stimulated with a strain of S. pyogenes isolated from children with bacteremia revealed that infection by this bacteria induces the expression of IL-2 messenger RNA (mRNA) and other cytokines." (PMID 27493590, 2016). "An interesting observation was the absence of any peripherally inserted central catheter (PICC) line-related infections or overt bacteremia despite 173 admissions with PICC-line placement for IL-2 therapy." (PMID 25815245, 2015). "Our study revealed that the cytokines IL-2, IL-6 and IL-10 were significantly higher in candidemia patients than in bacteremia patients, which was not reported in previous studies." (PMID 34684298, 2021). "However, other studies have shown conflicted findings in the serum level of IL-2, which were not significantly different in candidemia compared to bacteremia, whereas serum levels of IL-8, IFN-γ and TNF-α were non-significantly increased." (PMID 34684298, 2021). "Although populations of non-CD4 lymphocytes, such as CD8+ memory T cells, natural killer (NK) cells and double-negative (DN) T cells significantly expanded after IL-2/anti-IL-2 complex treatment, progressive development of bacteremia and pathologic lung alterations could not be prevented." (PMID 27391012, 2016). "The authors found that, during the first week, leukocytes have a reduced ability to produce IL-2 (interleukin-2), TNF-α (tumor necrosis factor-α) and IFN-γ (interferon-γ) in response to a non-self in patients with bacterial sepsis." (PMID 36982221, 2023). "In contrast, in sera from C57BL/6 mice exposed to MSHR5855, which did not exhibit appreciable bacteremia, we saw only a modest but significant increase in TNF-α, IL-2 and IP-10 but not until day 59 post-exposure." (PMID 30500862, 2018).
brain tumors (13 papers, 2008 to 2025). "LAK cells were generated by activating peripheral blood lymphocytes (PBLs) of patients with brain tumors using recombinant interleukin‐2 (IL‐2) over a period ranging from 3 to 7 days." (PMID 41030289, 2025). "In other studies, it was shown that a vaccine prepared by the transfer of a cDNA expression library, derived from tumor cells, into a mouse fibroblast cell line engineered to secrete IL-2 appears to be efficacious in the treatment of a brain tumor." (PMID 38002466, 2023). "Accordingly, both patients with brain tumors had a CSF cytokine profile with high IL-12, IL-13, and IL-2 concentrations." (PMID 37368708, 2023). "Although IL-2 had greater brain tumor responses, it also induced more severe toxicities elsewhere in the body, ultimately diminishing the patients’ quality of life and posing a threat for their overall survivability." (PMID 36983983, 2023). "Early results, however, have not revealed significant efficacy for prolonging survival in patients with brain tumors through the use various cytokines, including IL-2 and IL-15." (PMID 38002466, 2023). "On the other hand, the patients with brain tumors had increased levels of IL-12, IL-2, and IL-13 in their cytokine profile." (PMID 37368708, 2023). "We found that the frequencies of IFN-γ-, TNFα-, and IL-2-producing CD4+ T cells were increased in the brain tumour, spleen, and blood of EMP3_KO model mice." (PMID 33964937, 2021). "This antigen-specific response was further amplified in patients with brain tumor upon conditioning of whole blood with IL-2/IL-15/IL-21." (PMID 29970101, 2018). "We therefore concluded that the mesothelin-specific response of patients with grade IV brain tumors has potential to be enhanced with IL-2/IL-15/IL-21 conditioning." (PMID 29113296, 2017). "This is a stark representation of the general immune impairment in these individuals, which has been in part attributed to the reduced responsiveness of peripheral blood T cells from brain tumor patients to IL-2 further to the use of corticosteroids to reduce brain inflammation." (PMID 29970101, 2018). "Our hypothesis is that immune suppression from the brain tumor acts as an antagonist to IL-2 signaling in T cells, which is counteracted by the DC vaccine." (PMID 24883189, 2014). "We also evaluated the percentages of CD8+ and CD4+ T cells within the tumour, blood, and spleen and found that anti-PD-1 treatment of EMP3_KO tumour-bearing mice increased IFN-γ-, TNF-α- and IL-2-producing CD8+ and CD4+ T cell infiltration into the brain tumour, blood, and spleen." (PMID 33964937, 2021). "When we evaluated the percentages of IFN-γ-, TNF-α-, and IL-2-producing CD4+ and CD8+ T cells within GBM tumours, we noticed that CXCR3 blockade in the EMP3_KO group reduced CD8+ and CD4+ T cell infiltration into the brain tumour, blood, and spleen." (PMID 33964937, 2021). "In the reanalysis, we found that patients with grade IV brain tumour (GBM), constituting the majority of group of the study cohort, exhibited a significantly increased IFN-γ response to MPF and mesothelin precursor peptide pool if the PBMCS were conditioned with IL-2/IL-15/IL-21." (PMID 29113296, 2017). "The ommaya reservoir or infusion pumps have thus far been used in various clinical trials with brain tumor patients to interstitially deliver the chemotherapeutic agents BCNU or its analogs, methotrexate, adriamycin, bleomycin, fluodeoxyuridine, cisplatin, and interleukin 2(IL-2)." (PMID 20046703, 2008). "Notably, PBLs from brain tumor patients without activation by IL‐2 could not significantly destroy GBM cells." (PMID 41030289, 2025).
Chagas disease (13 papers, 2008 to 2025). A parasitic infection caused by Trypanosoma cruzi. "Trypanosoma cruzi infection is associated with severe T cell unresponsiveness to antigens and mitogens and is characterized by decreased IL-2 synthesis." (PMID 28114324, 2017). "The Trypanosoma cruzi infection is associated with severe T cell unresponsiveness to antigens and mitogens characterized by decreased IL-2 synthesis." (PMID 24204874, 2013). "In patients with Chagas disease and preserved EF, the presence of intraventricular conduction disorders appears to be associated with a distinct cytokine profile characterized by elevated IL-10, IL-12p70, IL-2, IL-15, MIP-1α, and IFN-γ." (PMID 41440541, 2025). "In conclusion, this study and others strongly suggest that the IL-2 pathway is an attractive target for manipulating Treg activity in Chagas’ disease." (PMID 34869064, 2021). "Early studies on Trypanosoma cruzi infection showed severe immunosuppression, and several mechanisms involving parasite antigens and host cell mediators were described as inhibition of IL-2 and IL-2R." (PMID 34513737, 2021). "We have previously shown that adult subjects with chronic T. cruzi infection have IFN-γ-producing T-cells responsive to T. cruzi antigens whereas IL-2 secreting cells are rare in Chagas disease patients." (PMID 28966620, 2017). "Therefore, the IL-2 pathway is an attractive target for therapeutic purposes in acute and chronic phases of Chagas’ disease." (PMID 34869064, 2021). "In addition, the in vivo administration of IL-2 or complexes of IL-2/anti-IL-2 to increase the numbers and functional activity of regulatory T cells would also be a valuable approach to be used in Chagas' disease." (PMID 27242702, 2016). "The notion concerning the manipulation of Treg cells either by antibodies to CD25, IL-2, and/or IL-10 might open up a new avenue for therapeutic strategies in Chagas' disease." (PMID 27242702, 2016). "Moreover, CD4+ T cells producing IL-2 are also impaired in Chagas disease patients further compromising the T cell function in these patients." (PMID 18846233, 2008). "Trypanosoma cruzi-specific T cell responses in children with Chagas disease and uninfected subjects living in non-endemic areas of Argentina, measured by IFN-γ and IL-2 ELISPOT." (PMID 24349591, 2013).
Erythema (13 papers, 2003 to 2025). Redness of the skin, caused by hyperemia of the capillaries in the lower layers of the skin. "Intralesional IL-2 therapy caused a dose-dependent inflammatory reaction at the site of injection with local swelling and erythema, which completely resolved within days of discontinuation of therapy." (PMID 14583759, 2003). "Administration of IL-2 following cell infusion was accompanied by local erythema at the site of injection in 22 patients, and malaise or mild fever responded to anti-inflammatory agents." (PMID 37202579, 2023). "Fatigue symptoms, erythema, and cytokine levels (IL-1β, IL-2, IL6, IL-8, TNF-α, and MCP-1) were registered at baseline, during treatment, and after radiotherapy completion." (PMID 24800238, 2014). "Among non-serious mild AEs, increased eosinophil count and injection site erythema were more common in both IL-2 treatment groups compared to placebo, aligning with previous reports of known side effect of low-dose IL-2 immunotherapies in other clinical contexts." (PMID 40615880, 2025). "The combination was well-tolerated: five patients developed expected, mild, and transient flu-like symptoms controlled by paracetamol, and two developed mild erythema around the IL-2 injection site, but no further adverse effects were observed." (PMID 35740670, 2022). "Mild erythema at injection site also occurred after IL-2 injection but, no GvHD was encountered." (PMID 39820676, 2025). "All patients tolerated treatment well: eight patients across both groups developed expected, mild, and transient flu-like symptoms controlled by paracetamol, and two developed mild erythema around the IL-2 injection site, but no further adverse effects were observed." (PMID 35740670, 2022).